IL18 (interleukin 18)
Diseases named in the same sentence as IL18 in open-access papers (continued):
Sharing a sentence is not in itself a finding about the gene and the disease.
cancer (continued). "However, the mechanisms for anti-cancer or pro-cancer effects of IL-18 have not been clearly understood yet." (PMID 31731729, 2019). "In addition, previous studies have revealed the effects of Erdr1 on cancer progression and its negative correlation with interleukin (IL)-18, a pro-inflammatory cytokine." (PMID 27941650, 2016). "Human monocytic THP-1 cells overexpressing a mutant variant of NLRP3 bearing the Q705K SNP have been reported to greatly respond to the inflammasome agonist alum and to trigger the production of IL-1β and IL-18, implying that overt NLRP3 activation could be detrimental for certain types of cancer." (PMID 25071785, 2014). "We suggest that the elevated levels of IL-18 gene expression upon treatment of Caco-2 cells with IBB109 and IBB417 may contribute to the stimulation of the immune system, leading to the recognition of cancer cells by the host organism, and thus, early prevention of disease development." (PMID 35694291, 2022). "In light of the results obtained from this study, it has been shown that there is a reduction in the local expression of the IL-18 mRNA, which suggests that it is a new mechanism, which may lead to the persistence of HPV in the epithelium and consequent onset of cervical neoplasias and cancer." (PMID 31554368, 2019). "And this study provided evidence that high NLRP3 inflammasome (NLRP3/IL-18/IL-1β/ASC) expression in LSCC cancer tissues suggests a poor prognosis of LSCC without distant metastasis in a Chinese population, which may help identify a new prognosis factor for LSCC." (PMID 31312615, 2019). "Short- and long-term administration of interleukin-18 appeared to have no adverse effects on the kidney in these mice, suggesting that administration may be a safe and novel treatment for metabolic diseases and cancer." (PMID 29514661, 2018). "To determine whether NLRP3 inflamasome was associated with human HNSCC, we examined their expression by immunohistochemistry and found that NLRP3, Caspase-1, ASC, IL-18 were highly expressed in the cytoplasm of cancer cells, and the expression of them was negative or low in the normal mucosa." (PMID 28865486, 2017). "Intracellular LPS-induced significant LDH release and increased secretion of IL-18 and IL-1β in IHGK and cancer cells, but not in normal HOKs, indicating selective cytotoxicity and pyroptosis." (PMID 40338411, 2025). "On the other hand, studies have shown that after normal intestinal epithelial cells become cancerous, they no longer produce IL18, resulting in down-regulation of IFN levels, which in turn allows cancer cells to escape from immune surveillance." (PMID 36707882, 2023). "Another study indicated that lactoferrin could up-regulate the components of non-specific immunity against cancer, including interferon-γ (IFN-γ), caspase-1 and interleukin-18 (IL-18)." (PMID 38298540, 2023). "In this study, we demonstrated that IL-18 alone did not affect HCT116 cells but promoted the antitumor ability of NK cells in a coculture with HCT116 cells via the miR-574-3p/TGF-β1 axis; this finding suggests that IL-18 can be the new potential target for cancer immunotherapy for CRC." (PMID 33660570, 2021). "Interestingly, we confirmed that P2X7 activation in TAMR-MCF-7 cells did not activate the classically known inflammasome pathways (IL-1β and IL-18), showing that P2X7 may control a non-canonical pathway in cancer cells." (PMID 31406126, 2019).
cardiovascular disease (82 papers, 2009 to 2025). "Several studies have suggested a potential association between the IL-18 promoter -137 G/C polymorphism and alterations in IL-18 expression, thereby potentially influencing the onset of cardiovascular disease (CVD)." (PMID 38792907, 2024). "Circulating IL-18 is moderately and independently associated with cardiovascular disease (CVD) and, also, higher levels of IL-1RA are positively associated with incident CVD." (PMID 36835948, 2023). "In cardiovascular disease patients, high IL-18 levels were associated with a risk of heart damage and death, supported by animal studies." (PMID 35251049, 2022). "It was shown that IL-18 as a proatherogenic cytokine was associated with the development of cardiovascular disease and all-cause mortality in stable heart disease patients independent of cardiac dysfunctions." (PMID 32297262, 2020). "A meta-analysis supported that circulating IL-18 was prospectively and independently associated with cardiovascular disease risk." (PMID 31661113, 2019). "In this study, we found that M-CSF is positively correlated with IL-6 and IL-18, suggesting M-CSF induced activation of IL-6 is related to M-CSF associated cardiovascular disease in patients undergoing maintenance hemodialysis." (PMID 31419967, 2019). "Serum IL-18 correlated positively with TC in AS; this is a well-known marker of the risk of cardiovascular disease." (PMID 27527149, 2016). "Although, cardiovascular disease and dysfunction are associated with increases in inflammatory cytokines such as IL-6 and IL-18 the large extent of cardiac I/R injury reported here does not correlate with the small changes in circulating cytokines." (PMID 27558113, 2016). "IL-18 is a relatively novel pro-inflammatory cytokine and recently associated with MetS with an independent but modest relationship to cardiovascular disease." (PMID 26225995, 2015). "In two prospective studies, elevated IL-18 levels were associated with future cardiovascular disease in previously healthy men and women." (PMID 20331890, 2010). "We had previously shown that one single nucleotide polymorphism (SNP) of the IL18 gene was associated with cardiovascular disease (CVD) through an interaction with smoking." (PMID 19473509, 2009). "The increased risk of cardiovascular disease correlates with high IL-18 levels." (PMID 37661270, 2023). "IL-18 is also known to play a pathogenic role in cardiovascular diseases." (PMID 35251049, 2022). "In this study, Mendelian randomization method was used to determine whether there was a causal association between inflammatory cytokine IL-18 and cardiovascular disease risk." (PMID 32264954, 2020). "There are several limitations in this study: Firstly, in this study, only IL-18-137G/C and IL-18-607 C/A were selected as IVs for Mendelian randomization study, which was inadequately powered to determine a true association between the IL-18 polymorphisms and cardiovascular disease." (PMID 32264954, 2020). "Mendelian randomization was subsequently unable to confirm whether the association between IL-18 levels and cardiovascular disease risk is a causal association." (PMID 32264954, 2020). "As IL-18 induces the production of TNFα which, in turn, supports the synthesis of IL-6, IL-18 might well be responsible for a high risk of cardiovascular disease in obese patients." (PMID 27747236, 2016). "In these processes, IL-18, a member of the proinflammatory interleukin family that is elevated in patients with cardiovascular disease, has been shown to be a potential key factor in postoperative inflammatory and ischemic responses." (PMID 40564918, 2025). "In these processes, IL-18, a member of the proinflammatory IL-1 family that is elevated in patients with cardiovascular disease, has been shown to be a potential key factor in postoperative inflammatory and chronic ischemic responses." (PMID 40564918, 2025).
cardiovascular disease (continued). "IL-18 has been firmly established as a pro-atherosclerotic agent in the development of cardiovascular disease with studies suggesting a major role in atherosclerotic plaque destabilization." (PMID 40503438, 2025). "Recent studies have highlighted pyroptosis-related molecules—particularly gasdermin D (GSDMD), interleukin-1β (IL-1β), and interleukin-18 (IL-18)—as potential biomarkers for cardiovascular diseases." (PMID 40832143, 2025). "IL-1β and IL-18 persist in damage to endothelial cells, which exacerbates synovial inflammation and cardiovascular disease in RA patient." (PMID 37063906, 2023). "We first assessed CAEC pro-inflammatory cytokine production for IL-6, TNF-α, IL-18 and IL-1β, which are four important players for the development of cardiovascular diseases together with the anti-inflammatory cytokine IL-10." (PMID 36992409, 2023). "It is exciting to notice that IL-18 is an essential key element that anticipates deaths due to cardiovascular diseases." (PMID 36677054, 2023). "Robust evidence has demonstrated a critical role for the NLRP3 inflammasome in the pathophysiology of various cardiovascular diseases (CVDs) owing to its ability to secrete the pro-inflammatory cytokines IL-1β and IL-18." (PMID 35806076, 2022). "Of course, IL-1β and IL-18 have great prospects as biomarkers for predicting the occurrence of cardiovascular diseases." (PMID 35647057, 2022). "Previous clinical studies have suggested a detrimental role of IL-18 in various cardiovascular diseases." (PMID 35251049, 2022). "Next, we measured interleukin release from classical monocytes obtained from acute and stable cardiovascular disease patients to assess if attenuation of rapid inflammasome activation affected IL18 production in monocytes from these patients." (PMID 35558073, 2022). "Our study suggests that IL18 is involved in the development of cardiovascular diseases through HIF-1 signaling pathway." (PMID 35069552, 2021). "Epidemiological studies have shown that the inflammatory factor IL-18 plays a very important role in the occurrence and development of cardiovascular diseases." (PMID 32264954, 2020). "Exogenous IL-18 inhibits endothelial differentiation in control EPCs/CACs; IFN-α contributes to an elevated risk of cardiovascular disease through suppression of the IL-1β pathway." (PMID 32528469, 2020). "In this context, activation of NLRP3 inflammasome mediating IL-1β and IL-18 secretion has emerged as an important component of inflammatory processes in cardiovascular diseases." (PMID 29245937, 2017). "The pro-inflammatory cytokine interleukin-18 (IL-18) is among the more recently recognized cytokines assumed to be involved in the development of cardiovascular disease (CVD)." (PMID 24040261, 2013). "Proteomic analysis in a subcohort revealed that higher levels of inflammatory and endothelial-related proteins (e.g., IL-18, TNF-R1/2, CSF-1, thrombomodulin, resistin) correlated with higher UPF intake, many of which were prospectively linked to cardiovascular disease." (PMID 41010537, 2025). "IL-18 is a pro-inflammatory cytokine in cardiovascular disease." (PMID 39334884, 2024). "IL-18 and IL-1β expressed by VSMCs play important roles in cardiovascular disease." (PMID 36527086, 2022). "This indicates that IL-18 is a potent mediator of cardiovascular diseases." (PMID 35251049, 2022). "The roles of IL18 in cardiovascular diseases and metabolic diseases are fully opposite." (PMID 36482059, 2022). "Both the NLRP3 inflammasome and its downstream cytokines, IL-1ß and IL-18, could therefore be promising targets in cardiovascular disease." (PMID 32648087, 2021). "IL-1β and IL-18, two key cytokines regulated by NLRP3 inflammasome activation, participate in endothelial inflammation and cardiovascular disease in humans." (PMID 32439949, 2020). "The authors conclude that serum IL-18 may serve as a predictor of the progression of DKD and cardiovascular disease." (PMID 38672515, 2024).
kidney disease (66 papers, 2012 to 2025). "In our study, IL-18 showed a strong positive linear correlation with all-cause kidney disease-related hospitalization or death." (PMID 35740095, 2022). "These pathways are altered in kidney disease and are linked to the production of vascular endothelial growth factor, erythropoietin, adiponectin, interleukin (IL)-18, IL-23, and chemokines that bind CXCR3, CXCR4, and/or CXCR7." (PMID 33676416, 2021). "Renal injury and fibrosis may be lessened by the loss or inhibition of IL-18, which offers a potential therapeutic target for the treatment of renal diseases." (PMID 40370722, 2025). "Renal disease activity remained statistically significantly associated with increased serum IL-18 after adjusting for organ damage and ethnicity, both of which attenuated their association with serum IL-18 in the multivariable model." (PMID 29930551, 2018). "A crucial proinflammatory cytokine secreted by macrophages, IL-18 contributes to inflammation and the advancement of renal disease." (PMID 40370722, 2025). "The NLRP3–ASC–caspase-1–IL-1β–IL-18 pathway has been identified as a factor in the development of the pathophysiology of numerous kidney diseases." (PMID 38740765, 2024). "Several animal studies have indicated that increased IL-18 secretion promotes the development of kidney diseases." (PMID 37624173, 2023). "The results showed that plasma SOD3 and serum IL-18 were two strong predictors of the first kidney disease-related hospitalization or death." (PMID 35740095, 2022). "Blood samples from all participants were collected for ROS, SOD3, IL-2, IL-6, and IL-18 measurement at the beginning of the study, and every kidney disease-related admission or death was recorded for the next year." (PMID 35740095, 2022). "In this study, we aimed to elucidate the correlation between different potential predictors (ROS, SOD3, hs-CRP, IL-2, IL-6, and IL-18) and first nephropathy-related hospitalization or death in ESRD patients receiving hemodialysis." (PMID 35740095, 2022). "This study aims to test the correlations between ROS, SOD3, IL-2, IL-6, and IL-18 and the first kidney disease-related hospitalization or death events in ESRD patients undergoing regular hemodialysis." (PMID 35740095, 2022). "Activation of NLRP3 inflammasome contributes to the maturation and release of proinflammatory factors such as IL-1β and IL-18, which is a vital component of inflammatory response and plays an important role in the progression of kidney diseases." (PMID 36212965, 2022). "Elevated IL‐18 levels in the circulation predict cardiovascular mortality in patients with kidney disease." (PMID 33336158, 2020). "Our data suggest that serum IL-18 and IL-1β have different clinical implications in SLE, with IL-18 being potentially associated with active renal disease." (PMID 29930551, 2018). "The roles of IL-1β and IL-18 in renal disease are well known, but the importance of inflammasomes in their activation has not been investigated." (PMID 29929501, 2018). "Univariable linear regression analyses showed that patients with active renal disease or irreversible organ damage had statistically significantly elevated serum IL-18 levels." (PMID 29930551, 2018). "Such a specific function for IL-18 in autoimmune lupus nephritis as well as in other kidney diseases already has been proposed previously." (PMID 26465326, 2015). "There is a better understanding of the role of IL-1 and IL-18 in renal disease, although the importance of the inflammasome in the activation and secretion of IL-1β and IL-18 has only been investigated recently." (PMID 24450291, 2014). "In fact, urine interleukin-18 (IL-18) has been shown to serve as an accurate biomarker to differentiate ATN from other etiological factors of renal disease." (PMID 24967242, 2014). "The most extensively studied component of the NLRP3 inflammasome in relation to renal disease is IL-18." (PMID 24450291, 2014).
kidney disease (continued). "Therapeutic interventions that modulate this pathway are being developed, and the functional significance of the inflammasome and the IL-1β/IL-18 axis in renal disease is of growing interest." (PMID 24450291, 2014). "Recent studies document the role of the NLRP3 inflammasome-caspase-1-IL-1β/IL-18 axis in kidney disease." (PMID 22701621, 2012). "The lack of association of urine IL-18 with kidney disease severity is in agreement with the results from the CRISP study, where urinary IL-18 did not associate with changes in eGFR or HtTKV in ADPKD patients with preserved kidney function." (PMID 38918734, 2024). "Thus, we propose that ASC and IL-18 can be used as theragnostic biomarkers of therapies targeting the inflammasome in kidney diseases." (PMID 35355862, 2022). "Urinary IL-18 is also expressed and secreted by macrophages in kidney diseases." (PMID 36263325, 2022). "In kidney biopsy analyses, increased glomerular and tubulointerstitial IL-1β protein was found in DKD compared to non-kidney disease control subjects, and IL-18 protein showed a stronger expression in tubular cells of diabetic patients compared to patients with minimal change nephrotic syndrome." (PMID 35204131, 2022). "Importantly, both IL-6 and IL-18 are upregulated by nuclear factor-κB (NF-κB) activation, triggering inflammation in cardiovascular and renal diseases." (PMID 34830289, 2021). "Continued research into the functions of macrophages and the IL-18/IL-23 balance may offer insight to the PD-1 axis in kidney disease." (PMID 33676416, 2021). "In conclusion: The crosstalk between immune cells and renal epithelium and the signal axes IFN-γ/chemokines and IL-18 could be the immune-mediated mechanisms of HEV-induced renal disorder." (PMID 32824088, 2020). "Although our study was conducted in a tertiary hospital in which patients were referred from several major regions in the country, our data showed common findings with the previous study; the correlation of IL-18 with renal disease activity and IL-6 with the non-renal disease have been described." (PMID 31842967, 2019). "IL-18 is well documented as being involved in various types of kidney diseases." (PMID 30717382, 2019). "This enhanced pyroptosis may be due to polymorphisms in the IL-18 gene, which have been linked to SLE and found to lead to heightened expression of IL-18 and development of kidney disease." (PMID 31781110, 2019). "Our data also indicate a strong association between serum IL-18, though not IL-1β, with renal disease activity in SLE." (PMID 29930551, 2018). "A decrease in the dampening of IL-18-mediated inflammation at the local level may thus contribute to active renal disease." (PMID 29422069, 2018). "To determine whether the inflammasome was activated in proteinuric kidney disease, we first detected the intensity and distribution of caspase-1, IL-1β and IL-18 staining which were the markers of inflammasome activation in the human renal biopsies." (PMID 23977286, 2013). "Because the pathophysiological events leading to kidney disease-related hospitalization or death included cardiovascular and infectious diseases, serum IL-18 concentration could act as an independent predictor for all-cause hospital admission or death better than other inflammatory mediators." (PMID 35740095, 2022). "Although based on in-vitro studies, NLRP3 inflammasome may have a role in the pathogenesis of renal diseases via overexpression of proinflammatory cytokines including IL-1β and IL-18, several pieces of evidence show that the NLRP3 effect may be independent of pro-inflammatory cytokine production." (PMID 34904012, 2021). "Among the AKIs, prerenal and intrinsic AKI frequently coexist that urinary neutrophil gelatinase-associated lipocalin (NGAL), interleukin-18 (IL-18), and albumin show clinically significant elevated concentration in renal disease patients than non-AKI patients do." (PMID 29258482, 2017).